CEMIP2 (cell migration inducing hyaluronidase 2)
Description:
Cell surface hyaluronidase that mediates the initial cleavage of extracellular high-molecular-weight hyaluronan into intermediate-size hyaluronan of approximately 10-5 kDa fragments. Very specific to hyaluronan; not able to cleave chondroitin sulfate or dermatan sulfate. Has an essential function in systemic hyaluronan catabolism and turnover and regulates cell adhesion and migration via hyaluronan degradation at focal adhesion sites (By similarity). Acts as a regulator of angiogenesis and heart morphogenesis by mediating degradation of extracellular hyaluronan, thereby regulating VEGF signaling (By similarity).
Synonyms: TMEM2
Tractability: Antibody: its Gene Ontology location is reachable by antibodies, with high confidence; UniProt places it where antibodies can reach, with medium confidence; UniProt predicts a signal peptide or a membrane-spanning region. PROTAC: ubiquitination databases record sites on it.
Gene: Protein-coding gene on chromosome 9 (71,683,364 to 71,816,690, reverse strand). Ensembl gene ENSG00000135048.
Subcellular location: Cell membrane
Subcellular location (Human Protein Atlas): Plasma membrane; Cytosol; Vesicles
Gene Ontology:
Molecular function: cadherin binding; calcium ion binding; hyalurononglucosaminidase activity
Biological process: regulation of sprouting angiogenesis; hyaluronan catabolic process
Cellular component: extracellular exosome; plasma membrane; membrane
Genetic constraint (gnomAD): Loss-of-function variants: 69 observed, 143.4 expected, observed/expected ratio (o/e) 0.48, 90% interval 0.4 to 0.59. The upper end of that interval is the gene's LOEUF score, 0.59, which puts it in group 2 of 6, group 1 being the genes least tolerant of losing a copy. Missense variants: 1,567 observed, 1,731.3 expected, observed/expected ratio (o/e) 0.91, 90% interval 0.87 to 0.94. Synonymous variants: 588 observed, 624.67 expected, observed/expected ratio (o/e) 0.94, 90% interval 0.88 to 1.01.
Homologues: Orthologues: chimpanzee CEMIP2 (99% identical), macaque CEMIP2 (99% identical), dog CEMIP2 (92% identical), rabbit CEMIP2 (92% identical), pig CEMIP2 (89% identical), guinea pig CEMIP2 (89% identical), rat Cemip2 (87% identical), mouse Cemip2 (87% identical), tropical clawed frog cemip2 (69% identical), zebrafish cemip2 (58% identical). Paralogues in human: CEMIP (42% identical).
Diseases named in the same sentence as CEMIP2 in open-access papers:
CEMIP2 is named in the same sentence as 31 diseases in open-access papers, as found by Europe PMC text mining. Sharing a sentence is not in itself a finding about the gene and the disease. The quoted sentences say what the papers report.
cancer (10 papers, 2021 to 2025). A tumor composed of atypical neoplastic, often pleomorphic cells that invade other tissues. "It is particularly important to understand the two pathways of HA degradation in malignant tumors, one involving HAYL1/HYAL2 and the other CEMIP/CEMIP2." (PMID 39858106, 2025). "Increased levels of LMWHA in malignant tumors suggest that HAS3, CEMIP, and CEMIP2 function as key enzymes." (PMID 39858106, 2025). "During cancer progression, hyaluronan synthase 2 (HAS2) and the cell migration inducing hyaluronidase 2 (CEMIP2, also known as TMEM2), are upregulated, promoting tumorigenesis." (PMID 35954411, 2022).
tumor (8 papers, 2020 to 2024). "However, a large number of genes considered as oncogenes or that promote tumour growth and/or metastasis, such as SKI, EGR4, SNAI1 and CEMIP2, were also overexpressed in response to TPL." (PMID 32543350, 2020).
CEMIP2 also shares sentences with these, for which no sentence is quoted: breast carcinoma (6 papers); diabetes (3); deafness (2); kidney disease (2); osteosarcoma (2); polycystic kidney disease (2); viral infection (2); ZIKV infection (2); acute lymphoblastic leukemia (1); bladder cancer (1); breast tumors (1); hepatitis B virus infection (1); Hypertelorism (1); infection (1); Inguinal hernia (1); laryngeal carcinoma (1); liver fibrosis (1); lung squamous cell carcinoma (1); metastatic tumors (1); mucinous adenocarcinoma (1); myopia (1); Obesity (1); ovarian carcinoma (1); pancreatic adenocarcinoma (1); prediabetes (1); prostate carcinoma (1); Retinal dystrophy (1); rheumatoid arthritis (1); Salmonella Infections (1).